CD4 (CD4 molecule)
Diseases named in the same sentence as CD4 in open-access papers (continued):
Sharing a sentence is not in itself a finding about the gene and the disease.
glioma (402 papers, 2008 to 2026). A benign or malignant brain and spinal cord tumor that arises from glial cells (astrocytes, oligodendrocytes, ependymal cells). "ALKBH5 loss fosters a more immunostimulatory microenvironment in glioma through an expanded T-cell presence-marked by increased CD4+and CD8+T lymphocyte counts and a higher CD8+/CD4+ ratio-coupled with a reduction in PD-L1 protein expression." (PMID 41522342, 2026). "Studies demonstrate that glioma-associated myeloid cells can suppress CD4+ T-cell antitumor activity, thereby facilitating tumor progression and contributing to immune evasion." (PMID 41272822, 2025). "In glioma, certain immune cells, such as neutrophils, macrophages, activated dendritic cells, and activated CD4+ T cells, are linked to worse outcomes." (PMID 41180518, 2025). "The increased ratio of Tregs to other CD4+ T cells has been associated with the glioma grade and, subsequently, patient prognosis." (PMID 39378431, 2025). "We found that higher levels of naïve B cells, plasma cells, naïve CD4 T cells, and activated mast cells were characteristic of TERTp-mutant glioma patients with high-risk scores in both TCGA cohorts, in association with a lower survival rate." (PMID 38499392, 2024). "DDOST was correlated with immune microenvironment in gliomas, which was related to infiltration of B cells, CD4 + T cells, tumor-associated macrophages and CAFs." (PMID 38460058, 2024). "Peptides including the mutated region were presented with MHC class II molecules and elicited a mutated specific CD4+ (TH1) immune response in mice models with IDH1 mutated gliomas, making it a possible neo-antigen for IDH1 mutated AMLs." (PMID 39770471, 2024). "TERTp-mutant gliomas with high-risk scores displayed a greater percentage of naïve B cells, plasma cells, naïve CD4 T cells, and activated mast cells than low-risk score gliomas." (PMID 38499392, 2024). "The majority of peptide vaccines under investigation for glioma aim to stimulate CD8+ T-cells or CD4+ T helper cells to target tumour-associated antigens (TAAs) or tumour specific antigens (TSAs)." (PMID 38660136, 2024). "Impaired CD4+ T effector memory cell function was associated with the proliferation of myeloid-derived suppressor cells (MDSCs) in glioma patients." (PMID 38926605, 2024). "As a result, we found RP2 was positively associated with the infiltration of Neutrophils, CD4+T cells, B cells, Dendritic cells, and Macrophages in glioma." (PMID 37602882, 2023). "Similar to this, we confirmed in our study that increased LILRB1 expression was linked to increased infiltration of B cells, CD4+T cells, M2 macrophages, neutrophils, and dendritic cells in patients with glioma." (PMID 37142967, 2023). "CD8+ T cells, naive CD4+ T cells, monocytes, M1 macrophages and M0 macrophages were in higher proportion in glioma tissues with low-risk scores." (PMID 37812190, 2023). "Analysis of immune cell infiltration in the present study showed that high NCAPG expression was significantly and positively associated with levels of B cells, CD8+ T cells, CD4+ T cells, macrophages, neutrophils, and dendritic cells in gliomas." (PMID 35280743, 2022). "Many immune cells, including glioma-associated macrophages (GAMs), CD4 + and CD8 + T lymphocytes, dendritic cells, T regulator cells, and NK cells, have an important role in GBM growth, migration, drug resistance, and response to immunotherapy." (PMID 35717510, 2022). "Mechanistic analysis revealed that DDOST was closely associated with the glioma microenvironment and negatively related to tumor-infiltrating B cells and CD4+ T cells and positively related to CAFs and tumor-associated macrophages." (PMID 35812432, 2022). "NDMI, total white cell count, and their interaction were significantly associated with CD4 T-cell levels in whole blood and explained substantial variation in CD4 counts among glioma subjects (r2 = 0.64; p < 0.001)." (PMID 36127421, 2022).
glioma (continued). "The NDMI is associated with low CD4 T cells and the accumulation of monocytic myeloid-derived suppressor cells and also serves as prognostic factor in glioma survival." (PMID 36127421, 2022). "We observed both gp96 overexpression and increased CD4/PD-1 immune cell densities associated with shortened OS time in glioma patients." (PMID 35794988, 2022). "TIMER database analysis showed that NID1 expression in low-grade gliomas was associated with tumor infiltration of B cells, CD4+ and CD8+ T cells, macrophages, neutrophils, and dendritic cells." (PMID 33735110, 2021). "As for the immune microenvironment of glioma, samples with higher risk demonstrated higher percentages of resting CD4+ memory T cells, M1, M2 macrophages, and activated dendritic cells in both cohorts." (PMID 34858984, 2021). "High risk gliomas were significantly enriched in negative regulation of the immunity pathway, such as negative regulation of B cells, CD4+ αβ cell activation, αβ T cell activation, and T cell differentiation." (PMID 32500034, 2020). "By contrast, subtype C3 included more grade II and IDH1-mutated glioma, and was associated with more infiltration of CD4+T cells." (PMID 33425739, 2020). "Glioma-associated CD73 was also shown to drive adenosinergic immunosuppression in concert with CD39 present on infiltrating CD4+CD39+ T lymphocytes." (PMID 31547570, 2019). "The higher percentage of CD8+ T cells and the ratio to CD4+ T cells in TILs have been reported to be associated with a favorable prognosis in patients with glioma." (PMID 31649684, 2019). "CD4+ and perivascular Foxp3+ TILs associate with tumor angiogenesis and tumor progression in glioma patients." (PMID 29163521, 2017). "Patients with high grade glioma undergoing treatment with temozolomide and fractionated radiation were found to have a lymphocyte decrease due only to loss of CD4 T cells, with the CD8 T cells remaining relatively stable." (PMID 27532020, 2016). "Accumulation and activation of CD4+FoxP3+ Tregs acts as a dominant immune escape mechanism for gliomas and underline the importance of controlling tumor-infiltrating Tregs in glioma immunotherapy." (PMID 24202450, 2013). "Previous studies have demonstrated that SERPINA3 expression is significantly enhanced in glioma and associated with poor prognosis for glioma patients, moreover, its expression have the potential to suppress the activation of CD4+ T cells, monocytes and Mast cells." (PMID 41550507, 2026). "DDOST is negatively correlated with tumor-infiltrating CD4+ T cells and B cells, and positively correlated with the presence of cancer-associated fibroblasts (CAFs) and TAMos, further highlighting the complex immune landscape of gliomas." (PMID 41272822, 2025). "Additionally, SERPINA3, a protein highly expressed in gliomas, is associated with poor prognosis and immune suppression, highlighting the essential role of CD4+ T cells in resisting tumor progression." (PMID 41272822, 2025). "The improved survival rate of S100a4−/− glioma-bearing mice was associated with the generation of anti-tumor immunity, accompanied by increased phagocytic activity of CD11b+ glioma-associated myeloid cells and enhanced activity of CD4+ T cells, stimulating T cell proliferation and IFNγ secretion." (PMID 38274827, 2023). "In a study revealing immune cell infiltration and immunotherapy in low-grade gliomas, high immune infiltration scores were significantly associated with increased levels of CD4 naïve T cell infiltration, and high CD4 naïve T cell expression suggested a good prognosis for patients." (PMID 37091853, 2023). "New studies also reported that DDOST could interact with the microenvironment of gliomas and was negatively related to tumor-infiltrating B cells and CD4+ T cells and positively related to CAFs and tumor-associated macrophages (TAMs)." (PMID 35812432, 2022).
glioma (continued). "Cox proportional hazard model analysis confirmed that the numbers of B cells, CD8+ T cells, CD4+ T cells, macrophages, neutrophils, and dendritic cells infiltrating into gliomas, as well as NCAPG expression, were associated with a poorer prognosis in glioma patients." (PMID 35280743, 2022). "The CD4+ T cell was linked to tumor angiogenesis and tumor progression in glioma patients." (PMID 34395626, 2021). "Moreover, Kaplan-Meier survival analysis revealed that high infiltration levels of M0 or Tregs, and low infiltration levels of monocytes, NK cell activation or T cell CD4+ naive were associated with poor prognosis and low survival rates of gliomas." (PMID 35118063, 2021). "The predominant population of CD4+ T cells may promote tumor angiogenesis, and in conjunction with perivascular CD4+ Tregs predispose tumor recurrence/progression in patients with gliomas." (PMID 29163521, 2017). "Moreover, myeloid TREM2 promotes MHCII-associated CD4+ T cell responses against gliomas." (PMID 39838454, 2025). "Therefore, CD4+ PD-1+ GITs were attracted to region near gp96+ glioma cells, further confirming the close association of gp96 expression with dysfunctional CD4+ T cell infiltration in gliomas, and suggesting an intrinsic mechanism that requires further investigation." (PMID 35794988, 2022). "Mice bearing GL-26 gliomas in the right corpus striatum when treated with direct intratumoral administration of replication-deficient adenoviral AdmIL-12 vector, it significantly prolonged the survival of glioma bearing animals with robust infiltration of CD4+ and CD8+ T-cells." (PMID 33790740, 2021). "Furthermore, a larger fraction of CD4+ resting T cells and Tregs were found in high-risk cases, whereas the fractions of CD4+ naïve T cell, CD4+ activated T cell, and gamma delta T cells were extremely low in the tested glioma cases." (PMID 34650975, 2021). "A study on glioma CAR-T therapy revealed that lactate induces H3K18 lactylation in CD4+ T cells and Tregs." (PMID 41463052, 2025). "The results indicated that inhibiting ADORA1 increased the recruitment of CD8+ and CD4+ T cells in gliomas, thereby benefiting from PD-L1-targeted immunotherapy." (PMID 40376586, 2025). "CD4+ T cells, particularly their regulatory and effector subsets, are crucial for both promoting and regulating immune responses in glioma." (PMID 41272822, 2025). "Compared with IDH-wildtype glioma cells, IDH-mutant glioma cells show a lower infiltration of both CD4+ and CD8+ lymphocytes." (PMID 40428422, 2025). "CD4+T cells were significantly increased in the glioma tissue of the ITE+PD1 group, which was further confirmed by immunostaining of the tissue, indicating a local expansion rather than recruitment from the spleen." (PMID 40283908, 2025). "These Tregs are key drivers of immune suppression within tumors, dampening CD4+ T-cell antitumor responses and contributing to the immunosuppressive milieu that enables glioma survival and growth." (PMID 41272822, 2025). "Preclinical glioma studies show that CTLA-4 inhibitors promote CD4+ T cell proliferation and reduce Treg/CD4+ T cell ratios, correlating CTLA-4 expression with poor prognosis in glioblastoma." (PMID 39911397, 2025). "ESTIMATE and CIBERSORT analysis demonstrated that gliomas have a higher proportion of macrophage cells and CD4 cells." (PMID 41551155, 2025). "On the 14th day after treatment, glioma tissues were collected from the mice, and the infiltration of CD8+ T cells and CD4+ T cells in the glioma was analyzed using immunohistochemistry." (PMID 41381536, 2025). "Our analysis showed a positive correlation between SMC4 expression in gliomas and CD4 T cell activation." (PMID 39949776, 2025). "Resting memory CD4+ T cells exhibited the highest abundance in meningiomas and the lowest in lower-grade gliomas (Kruskal–Wallis test, p < 0.0001)." (PMID 38540119, 2024).
glioma (continued). "Although CD8+, Treg, and conventional CD4+ T cells make up 1–5% of glioma cells, most of them lack anti-tumor activity." (PMID 39452154, 2024). "Using the CIBERSORT cohort, we showed that gliomas with MAN1C1High expression exhibited increased infiltration of immune cells, including neutrophils, MO/M2 macrophages, and CD4 + T cells, and decreased infiltration of CD8 + T cells." (PMID 39333557, 2024). "In gliomas, the expansion of Tregs can potentially induce tolerance by diminishing the activation signals from CD4+ helper T-cells to CD8+ T-cells." (PMID 39452154, 2024). "In this regard, TMZ has been shown to be pro-phagocytic to glioma cells and increases the cross-priming of tumour antigen-specific CD4 + and CD8 + cells." (PMID 39048947, 2024). "Compared to normal tissue, glioma samples exhibiting MAP3K1 arm‐level deletions showed significantly increased infiltration of CD4+ T cells, neutrophils, and dendritic cells." (PMID 39443331, 2024). "Intratumoral TIM-3 expression by CD4+ and CD8+ T-cells was found to be higher in GBM compared with low-grade glioma, suggesting an association with glioma severity." (PMID 38660136, 2024). "In mouse models of glioma as well as colon and pancreatic cancer, elevated levels of CD4+ TILs were reported in KD compared to standard diet-fed mice, whereas the number of CD4+ TILs remained unchanged in another murine colon cancer model." (PMID 39537934, 2024). "CD8+ T cells play a vital role in tumor clearance, and a higher presence of tumor-infiltrating CD4+ and CD8+ T cells is linked to extended patient survival in glioma." (PMID 39452154, 2024). "Comparable to ALE, IDH-wildtype glioma patients were characterized by a pronounced PB and CSF adaptive immune response with an increase in activated CD4+ and CD8+ Tc in PB and CSF, and Bc in CSF." (PMID 39497174, 2024). "T cells, including CD8+ cytotoxic T lymphocytes (CTLs), regulatory CD4+ (Treg), and conventional CD4+ T cells, constitute 1–5% of the total glioma cellular content." (PMID 38254796, 2024). "Directly comparing ALE with IDH-WT glioma, activated CD4+ Tc were even higher in IDH-WT glioma than in ALE patients, whereas CD4+ were elevated in the PB of ALE patients." (PMID 39497174, 2024). "In this study, we also found that the M2 macrophages and memory CD4+ T cells tend to enriched in glioma samples of HIS subtype, which eventually leads to poor prognosis." (PMID 38613347, 2024). "T lymphocytes, CD8+ cytotoxic T cells, and CD4+ helper cells play crucial roles in other tumors; however, in glioma immunity, they act as both anti-tumor agents and facilitators of immune evasion." (PMID 39452154, 2024). "A previous study showed that EGFR-mutant cases exhibit increased infiltration of CD4+ T cells, neutrophils, macrophages, and dendritic cells, leading to a poor prognosis in low-grade gliomas." (PMID 39139341, 2024). "There is no clear association between tumor-infiltrating lymphocytes (CD3+, CD4+, or CD8+ T cell infiltrates) and overall survival in patients with glioblastoma/glioma." (PMID 38481999, 2024). "Isolated CD4+ T cells from glioma-mice-lymph nodes have been shown to upregulate inhibitory molecules, such as CTLA-4 and PD-1, and decrease IL-2 production compared to CD4+ T cells isolated from engrafted tumors with LAMP-2AKO pericytes." (PMID 39086395, 2024). "Our studies showed that naive CD4 T cell infiltration was reduced in the tumor microenvironment of glioma patients with high IGFBP3 expression." (PMID 38326861, 2024). "Analysis of peripheral blood obtained from patients with glioma showed shifts in the normal CD4+/CD8+ T cell ratio (from 2:1 closer to 1:1)." (PMID 38481999, 2024). "We have recently published that functional activation of CD4+ T cells by glioma-infiltrating myeloid cells is a major determinant of CD8+ T cell fitness and prevents their differentiation into terminally exhausted T cells." (PMID 38306431, 2024).
glioma (continued). "Increased expression of granzyme A, granzyme B, and perforin by intratumoral CD4+ CTLs in gliomas suggests these cells to be a positive prognostic marker for glioma survival." (PMID 37304294, 2023). "Elevated circulating Hsp70 levels and a higher prevalence of activated CD3−/CD56+/CD94+/CD69+ NK cells were associated with an improved OS in grade 3 gliomas, whereas high Hsp70 levels and low CD3+/CD4+ frequencies were associated with an adverse OS in GBM." (PMID 38137456, 2023). "The results showed that the levels of infiltrating B cells, CD8+ cells, CD4+ T cells, macrophages, dendritic cells, and neutrophils were related to the cumulative survival rate of glioma patients." (PMID 36714030, 2023). "Previous studies showed that high-grade gliomas exhibit high levels of CD4+ but low levels of CD8+ TILs." (PMID 37274252, 2023). "In contrast, CD4 T cells, Tr1s, nTregs, iTregs, Th1s, and Th17s infiltrating the glioma tumor microenvironment were correlated with immunosuppression and a poor prognosis." (PMID 37261362, 2023). "The results showed that the expression of PLEKHA4 was positively correlated with the infiltration level of B cells, CD8+ cells, CD4+ T cells, macrophages, dendritic cells, and neutrophils in glioma." (PMID 36714030, 2023). "More importantly, 131I-hu4G4 remodeled the tumor microenvironment and promoted the transformation of glioma from “cold” to “hot” tumors by promoting CD4+ and CD8+ T cell infiltration and the polarization of M2 to M1." (PMID 37705739, 2023). "Tregs exert considerable immune-suppressive effects in gliomas, and generally increase with the reduction of anti-tumor CD4+ T cells fraction." (PMID 36845382, 2023). "(ii) A bulk RNA-seq dataset of sorted immune cell types from the TME of human gliomas was helpful to separate GBM-associated CD4+ and CD8+ T cells, as well as microglia and MdMs." (PMID 38127790, 2023). "REST expression was significantly associated with all analyzed immune cells, including B cells, CD8+ T cells, CD4+ immune cells, macrophages, neutrophils, and dendritic cells in glioma (P < 0.001)." (PMID 36810892, 2023). "Previous studies have found that naive CD4+ T cells, activated mast cells and monocytes are protective factors for the prognosis of glioma patients." (PMID 38115820, 2023). "Gliomas of CDNP-R848 treated mice depicted an altered T cell composition with increased CD4+ T cell proliferation and decreased Lag3-mediated T cell exhaustion, likely driven by IL-12 upregulation." (PMID 36774352, 2023). "TGF-β2 has been observed to mitigate the recognition of glioma cells by CD4+ T lymphocytes through reducing the expression of HLA-DR antigen on human glioma cells." (PMID 37790751, 2023). "These cells promote tolerance of glioma cells by other effector T cell populations (CD4+ and CD8+) via secretion of transforming growth factor β (TGF-β) and IL-10." (PMID 37046685, 2023). "A high level of CD4+ tumor-infiltrating lymphocytes (TILs) with a low level of CD8+ TILs is associated with poor prognoses, which has been reported in glioma patients." (PMID 36915911, 2023). "Specifically, the role of Th17 cells, a subpopulation of effector CD4+ helper T cells that produce IL-17A, in the effectiveness of glioma immunotherapy continues to be a subject of extensive discussion." (PMID 38274827, 2023). "has discovered co-culture of naive T cell with glioma-associated MDMs can induce a differentiation into TGFBI and IL-10 secreted CD4+ Treg cell." (PMID 36761752, 2023). "In this study, we demonstrated that TIO3 also broadly inhibits sTGF-β2 expression in tumor cell lines and glioma tissues, as well as in antitumor effector CD4+ and CD8+ T cells." (PMID 36776837, 2023). "SLC1A5 expression correlated positively with immune cells, such as tumor-infiltrating B cells, CD4+ T in hepatocellular carcinoma, and lower-grade glioma." (PMID 35359663, 2022).